CRP (C-reactive protein)
Diseases named in the same sentence as CRP in open-access papers (continued):
Sharing a sentence is not in itself a finding about the gene and the disease.
Hyperglycemia (continued). "Higher values of ESR had predictive and diagnostic value for the onset of complication events, and higher values of CRP and hyperglycemia were diagnostic factors since they were elevated during the occurrence of an event." (PMID 33266483, 2020). "By contrast, the elevation of CRP and hyperglycemia were diagnostic factors since their elevation occurred during the occurrence of the event." (PMID 33266483, 2020). "We have found that severity of hyperglycemia is associated with increased high-sensitive C-reactive protein (hs-CRP) in the cell free plasma of diabetic individuals." (PMID 28811499, 2017). "In another prospective, randomised, parallel clinical study, it was demonstrated that individuals with MetS are prone to exhibiting low urinary pH, alterations in CRP levels and increased susceptibility to GO attacks, particularly in cases exacerbated by chronic hyperglycaemia and hyperlipidaemia." (PMID 39789419, 2025). "In the severe hyperglycemia group (>300 mg/dL), notable correlations were observed: CRP was inversely associated with oxygen saturation and positively with radiologic severity and D-dimer levels, suggesting an intense systemic inflammatory syndrome with pulmonary and vascular involvement." (PMID 41156159, 2025). "These abnormally present cytokines inhibit insulin signalling in hepatocytes, resulting in impaired suppression of gluconeogenesis causing hyperglycaemia, which then leads to an increased production of very low-density lipoprotein and C-reactive protein levels." (PMID 38202263, 2024). "Therefore, differentiating between acute and acute-on-chronic hyperglycaemia enabled us to assess the effect of acute hyperglycaemia on CRP levels, most likely triggered by the stress associated with CAP." (PMID 38202252, 2023). "In addition to lower PFR, elevated levels of NLR, CRP, IL-6, and TyG index were highly associated with an increased incidence of hyperglycemia on admission." (PMID 37515156, 2023). "In a prospective cohort study of adults with CAP, the associations between chronic, acute, and acute-on-chronic hyperglycaemia (admission glucose minus HbA1c-derived average glucose) and CRP levels until admission day 3 were modelled with repeated-measures linear mixed models." (PMID 38202252, 2023). "Factors independently associated to HCRI were hyperglycemia (OR = 12.8 [3.1–51]), elevated CRP (> 115 mg/l, OR = 1.009 [1.001–1.017]), steroid use duration > 10 d (OR = 1.25 [1.08–1.44]), arterial catheter (OR = 6.57 [1.35–31]) and bladder catheterization (OR = 43)." (PMID 35729416, 2022). "In the acute phase of GBS at admission, hyperglycaemia and higher CRP occur relatively frequently, and may be a risk factor for the severity of GBS." (PMID 35677334, 2022). "In addition to the common risk factors often reported even outside of COVID, hyperglycemia, elevated CRP, and prolonged corticosteroid duration were the original factors found associated with HCRIs in our cohort." (PMID 35729416, 2022). "Salivary CRP and insulin were significantly associated with intermediate hyperglycemia at the 75th percentile cutoffs suggesting that a predictive value of the biomarkers such as levels found in serum could be indicative of diseases." (PMID 35757631, 2022). "IL-6 and CRP are associated with hyperglycemia and insulin resistance." (PMID 33530554, 2021). "CRP is known to associate with hyperglycemia, and predicts the risk of type 2 DM." (PMID 33998259, 2021). "Various factors that have been associated with poor outcome include altered sensorium, hypertensive etiology, hyperglycemia, longer time to control the causative factor, elevated C reactive protein, coagulopathy, extensive cerebral edema, and hemorrhage on imaging." (PMID 32117030, 2020). "Furthermore, we found an association between serum hs-CRP and hyperglycemia." (PMID 31143476, 2019). "To comprehensively evaluate their combined contribution, we proposed the high-sensitivity C-reactive protein-stress hyperglycemia ratio (CSR)." (PMID 41929469, 2026).
Hyperglycemia (continued). "Those with MLTC were older, had higher BMI, greater hyperglycaemia and had higher levels of triglyceride and C-reactive protein (CRP)." (PMID 41353206, 2025). "Across all groups, LDH correlated positively with ferritin, AST, and CRP, but these correlations were strongest in the moderate hyperglycemia subgroup, pointing to multisystem cellular injury." (PMID 41156159, 2025). "This rate exceeded that reported for extreme hyperglycemia (≥500 mg/dL; 4.6%, 16/351) and severe elevation of CRP (≥40 mg/dL; 16.0%, 44/275); however, it was lower than the fatality rate for severe AST elevation (≥3,000 U/L; 31.1%, 133/428)." (PMID 40242697, 2025). "The observed strong positive correlation between HbA1C and CRP (r = 0.72, p < 0.001) reinforces the concept that hyperglycemia perpetuates systemic inflammation, which in turn adversely affects wound healing." (PMID 41367458, 2025). "Subsequent blood tests revealed increased C-reactive protein (75.5 mg/L) and slightly raised lactate (3.5 mmol/L), with persistent hyperglycemia (181 mg/dL)." (PMID 41552160, 2025). "At the same time, the inactivation of protein kinase C (PKC) and C-reactive protein (CRP) in the serum of diabetic mice after hyperic acid administration was documented due to suppression of marked hyperglycemia." (PMID 39796209, 2025). "ESR and CRP are significantly elevated in patients with glucose levels >300 mg/dL, suggesting heightened inflammatory processes in severe hyperglycemia." (PMID 40075801, 2025). "While our study did not assess pro-inflammatory cytokines, systemic inflammation markers such as ferritin, ESR, and CRP were significantly elevated in patients with glucose levels >300 mg/dL, reflecting an enhanced inflammatory response due to hyperglycemia." (PMID 40075801, 2025). "Baseline evaluation showed polycystic ovaries with >15 antral follicles each, markedly elevated testosterone (140.3 ng/dL), 17-hydroxyprogesterone (218 ng/dL), hyperglycemia, and elevated C-reactive protein (CRP; 44.4 mg/L)." (PMID 41153771, 2025). "Acute and persistent hyperglycemia increases intercellular adhesion molecule-1 levels and other inflammatory molecules (tumor necrosis factor-α, CRP), which would augment plugging of platelets and leukocytes in the capillaries." (PMID 40863381, 2025). "In FBG-based assessments, NHR exhibited better discriminatory ability for hyperglycemia than the classical inflammatory marker CRP." (PMID 41373239, 2025). "In mild hyperglycemia, the network remained relatively simple, with correlations primarily restricted to inflammatory markers (CRP, ESR, fibrinogen, ferritin, LDH) and hematological parameters (leukocyte and lymphocyte counts)." (PMID 41156159, 2025). "Hyperglycemia is known to deactivate monocytes, increase C-reactive protein and inflammation, and reduce immune function." (PMID 38552059, 2024). "HDL, however, remained a significant independent predictor for intrahospital mortality even after additional correction for initial CRP, HbA1c, admission blood glucose, and stress hyperglycaemia ratio (SHR) in respective separate models." (PMID 39685701, 2024). "The current study synthesized evidence from clinical trials to evaluate the potential benefits of curcumin on hyperglycemia and CRP in T2D patients." (PMID 39683570, 2024). "Findings from our study reaffirm the significance of preventable and controllable factors, including HBP, hyperglycemia, elevated CRP, D-dimer, and homocysteine concentrations, as well as, ACR, as potential risk factors for cognitive decline and AD/ADRD." (PMID 38628973, 2024). "It has been reported that inflammation, indicated by C-reactive protein (hs-CRP), and hyperglycaemia, indicated by haemoglobin A1c (HbA1c), jointly contribute to the cardiovascular risk of patients with metabolic disease complications." (PMID 39156131, 2024).
Hyperglycemia (continued). "The current study is consistent with literature reports that an increasing trend in CRP was observed in hyperglycemia, in comparison to normal or borderline state." (PMID 38212326, 2024). "Upon admission, the patients presented hyperglycaemia, leucocytosis, and inflammatory syndrome (higher C-reactive protein)." (PMID 39768881, 2024). "This study investigated the associations firstly between chronic, acute, and acute-on-chronic hyperglycaemia and CRP levels, and secondly between admission CRP levels and IR in CAP." (PMID 38202252, 2023). "While inflammatory indicators, such as WBC count, CRP, and d-dimer, were raised in many patients, our most remarkable finding was the high frequency of hyperglycemia (seen in more than four-fifths of the patients)." (PMID 37724226, 2023). "Nevertheless, our study adds to the current literature by evaluating the impact of acute-on-chronic hyperglycaemia on CRP levels." (PMID 38202252, 2023). "Hyperglycemia (OR 1.40, 95% CI 1.09–1.81, p = 0.010), low serum levels of DHEA-S (OR 3.33, 95% CI 1.32–8.41, p = 0.011), and high serum levels of C-reactive protein (OR 1.45, 95% CI 1.05–2.00, p = 0.023) were associated with low IC at baseline." (PMID 36750172, 2023). "Admission CRP levels were similar, with overlapping 95% CIs between groups when stratified by chronic, acute, or acute-on-chronic hyperglycaemia." (PMID 38202252, 2023). "The peak CRP levels were on day 1 and similar between groups when stratified by chronic, acute, or acute-on-chronic hyperglycaemia." (PMID 38202252, 2023). "Previous studies have shown that this miRNA is one of the lipid metabolism-related miRNAs, and its upregulation correlates with hyperglycemia, hyperlipidemia, and inflammation markers, such as CRP and IL-1β." (PMID 36989330, 2023). "This study provides important longitudinal data linking the development of hyperglycemia through CRP and insulin salivary inflammatory biomarkers." (PMID 35757631, 2022). "Using a nationwide population-based survey, our results demonstrated that the integration of high levels of inflammation, such as CRP, and hyperglycemia, such as HbA1c, showed higher odds of MCI." (PMID 35252292, 2022). "Compared with the non-hyperglycemia group, the hyperglycemia group had much intense inflammation (CRP 77.30 ± 100.20 vs. 96.12 ± 83.38 mg/L) (p = 0.016)." (PMID 35721170, 2022). "Similar results have proved that insulin group and hyperglycemia have more enhanced systemic inflammation and higher inflammatory markers including D-dimer, C-reactive protein, TNF-a and other interleukins." (PMID 35725489, 2022). "It has been shown that 6-gingerol has renoprotective effects in diabetic rats due to its ability to regulate urea and creatinine levels, inhibiting oxidative stress, hyperglycemia, and inflammatory markers such as CRP, IL-6, IL-1, and TNF-α." (PMID 36557312, 2022). "Hyperglycemia had a direct effect on mortality, the indirect effect was only through absolute neutrophil count, CRP and PCT and markedly lower than the direct one." (PMID 36371199, 2022). "To determine the dietary patterns related to inflammation and hyperglycemia, we attempted to explore dietary patterns related to higher CRP and HbA1c levels and to express the effects of dietary patterns and particular food groups on MCI." (PMID 35252292, 2022). "DiabeticPMW were more susceptible to the deleterious effects of hyperglycemia than men,showing microvascular dysfunction with high levels of pro-inflammatory mediators(CML and CRP) and a lower adiponectin concentration." (PMID 35239779, 2022). "Hyperglycemia had a direct effect on mortality (p < 0.001); the indirect, through inflammatory markers, was significant only for absolute neutrophil count, C-Reactive protein and procalcitonin (p = 0.007, p = 0.029, p = 0.042)." (PMID 36371199, 2022). "Laboratory findings revealed hyperglycemia, elevated erythrocyte sedimentation rate 118 mm/hour, and elevated C-reactive protein 6.58 mg/dL." (PMID 35331322, 2022).
Hyperglycemia (continued). "A study on the Indian population also revealed that there is a correlation between CRP and hyperglycemia." (PMID 37654824, 2022). "The expression of the same proinflammatory cytokines implicated in hyperglycemia (IL-6, TNF-α, and CRP) has been reported to be associated with oral infection and PD." (PMID 34068221, 2021). "In our analysis, the association with DPN remained unchanged for sTNFRI, sTNFRII, sIL2Rα, IGFBP6 and CRP, after adjusting for HbA1c levels in study subjects, suggesting that factors other than hyperglycemia are also involved in pathogenesis of DPN." (PMID 33868296, 2021). "R-7050 also reduced the metabolic alterations occurring after ischemic stroke, such as hyperglycemia and increased plasma corticosterone, free fatty acids, C reactive protein, and fibroblast growth factor-15 concentrations." (PMID 34073455, 2021). "Patients presented with hyperglycemia were more likely to have higher levels of IL-6, IL-18 and hs-CRP compared to the normoglycemic patients." (PMID 34117510, 2021). "R-7050 treatment improved fasting hyperglycemia and glucose intolerance, accompanied by lower plasma levels of corticosterone, free fatty acids, and CRP." (PMID 34073455, 2021). "In order to test the mediatory effect of these variables, we carried out a formal mediation analysis where LDH, hyperglycaemia (glucose > 8mmol/l) and CRP were fitted as mediators of the effect of BMI on severity." (PMID 33851033, 2021). "Children with excessive weight; abdominal obesity; increased gynoid and android body fat; low HDL-c; hyperglycemia; and elevated uric acid, homocysteine, and apoB had higher chances of presenting increased hs-CRP (P < 0.05)." (PMID 31143476, 2019). "Researches have shown that plasma levels of interleukin 8 (IL-8) and C-reactive protein (CRP) are higher in patients with hyperglycemia than in patients with normal BG levels, thereby reducing T cell expression and the body’s immune response." (PMID 31847835, 2019). "In summary, CTRP1 is correlated with several factors such as chronic hyperglycaemia (HbA1c), inflammation (CRP), renal function (creatinine) and liver injury (bilirubin), making it challenging to dissect its clinical relevance from confounding factors." (PMID 31083558, 2019). "The hyperglycemia can directly enhance an inflammatory state by regulating C-reactive protein (CRP) and cytokines, such as interleukins, which is involved in the development of cardiovascular diseases." (PMID 30073019, 2018). "DM, hyperglycemia, and impaired glucose tolerance are associated with increased levels of IL-6, tumor necrosis factor (TNF)-α, and C-reactive protein (CRP)." (PMID 30298057, 2018). "Two dogs had mild hyperglycemia (6.84, 7.2 mmol/l; reference interval 3.7–6.6 mmol/l) and elevated CRP (52, 57 mg/l; reference interval <20 mg/l)." (PMID 28468664, 2017). "We report here an important role of human CRP in Type 2 diabetic kidney disease as CRPtg-db/db mice developed much more progressive kidney injury including higher levels of hyperglycemia, microalbuminuria, and excessive renal inflammation and fibrosis." (PMID 27221338, 2016). "The mononuclear cells of women with PCOS are increased in this inflammatory state, which occurs more often in response to hyperglycemia and C-reactive protein (CRP)." (PMID 27423183, 2016). "Combined rise of hs-CRP and uric acid was associated with severity of MetS (p < 0.001) and higher odds for hyperglycemia (8.036; 2.178–29.647, p = 0.001) as compared to individual rise of hs-CRP or uric acid." (PMID 27006878, 2016). "Clinical data showed that hyperglycemia and neurologic complications were significantly higher in EV71-infected patients, while upper respiratory tract infection and C-reactive protein were significantly higher in CVA16-associated patients." (PMID 24776922, 2014).
Hyperglycemia (continued). "Compared to patients with postprandial type hyperglycemia, those having fasting type hyperglycemia had significantly higher serum triglyceride, hs-CRP, and ALT concentrations." (PMID 23880900, 2014). "Elevated CRP (levels of greater than 2 mg/L of plasma CRP) increases blood glucose levels with the cascading impact of hyperglycaemia illustrated above." (PMID 23094144, 2012). "The mononuclear cells of women with PCOS are increased in this inflammatory state, which occurs more so from a heightened response to hyperglycemia and C-reactive protein (CRP)." (PMID 22748101, 2012). "Blood tests were performed, revealing hyperglycemia and a slight increase in C-reactive protein." (PMID 41552160, 2025). "Marked hyperglycemia (256 mg/dL) and a mildly raised C-reactive protein led to hospital admission." (PMID 41552160, 2025). "Elevated CRP and blood glucose levels (p < 0.001 for both) were also observed, indicating systemic inflammation and possible metabolic disturbances, such as stress-induced hyperglycemia." (PMID 39859111, 2025). "Elevated levels of cortisol and inflammatory biomarkers such as C-reactive protein (CRP) and interleukin-6 (IL-6), common to both conditions, may contribute to both hyperglycemia and depressive symptoms." (PMID 40726880, 2025). "Similarly, poor glycemic control, reflected by higher HbA1c levels, correlated with both elevated CRP and more severe ulcer grades, underscoring the synergistic interplay between hyperglycemia and systemic inflammation in DFU pathophysiology." (PMID 41367458, 2025). "Additionally, advanced glycosylation products, which are by-products of hyperglycemia, and even glucose itself, can increase the production of inflammatory cytokines like IL-6 and CRP." (PMID 40951890, 2025). "Furthermore, this study highlights the role of hyperglycaemia and elevated CRP levels as predictors of future cardiovascular events, emphasizing their importance as key risk markers in post-MI patients." (PMID 38921434, 2024). "Therefore, Curcuma longa and its active compound, curcumin, can improve hyperglycemia and inflammation by reducing fasting blood glucose, glycated hemoglobin, and C-reactive protein." (PMID 39683570, 2024). "Although patients with prediabetes were prescribed glucocorticoids more often than the other chronic hyperglycaemia groups, adjusting for glucocorticoid therapy did not modify the association between chronic hyperglycaemia and CRP levels." (PMID 38202252, 2023). "In the present study, a significant increase in CRP was also observed in the PG after follow-up, which may be due to chronic low-grade inflammation arising as a consequence of the hyperglycemia that characterizes T2D." (PMID 37108584, 2023). "The elevation of CRP levels observed in our experiment may have resulted in response to persistent hyperglycemia occurring in diabetic group, as suggested by many pervious reports." (PMID 36984840, 2023). "We observed a significantly lower lymphocyte count, higher NLR, and higher IL-6 and CRP levels in patients with mild and intermittent hyperglycaemia, presuming that the inflammatory response is more pronounced in patients with increased glucose levels at admission." (PMID 38255162, 2023). "Identifying how hyperglycaemia affects CRP levels could significantly enhance the management of CAP by improving risk stratification and guiding treatment decisions based on a patient’s glycaemic status." (PMID 38202252, 2023). "We tried to analyse if hyperglycaemia and CRP at admission may influence the outcome of GBS, including mechanically ventilated (MV) patients." (PMID 35677334, 2022). "Hyperglycemia and increased serum CRP levels are characteristic features of uncontrolled T2DM." (PMID 37654824, 2022).